RHOA (ras homolog family member A)
Diseases named in the same sentence as RHOA in open-access papers (continued):
Sharing a sentence is not in itself a finding about the gene and the disease.
renal fibrosis (19 papers, 2015 to 2025). A final common manifestation of a wide variety of chronic kidney diseases characterized by glomerulosclerosis and tubulointerstitial fibrosis. "Collectively, this study provides novel insights into NAE1-dependent RhoA neddylation as a key contributor to renal fibrosis in DN." (PMID 39900822, 2025). "Given the marked influence of NEDD8 on RhoA protein stability in renal fibrosis, we investigated its role in the regulation of RhoA protein expression during profibrotic pathogenesis." (PMID 39900822, 2025). "This study identified the neddylation of RhoA as a novel post-translational modification that regulates its expression and promotes renal fibrosis in DN." (PMID 39900822, 2025). "LncRNA NEAT1 accelerates renal fibrosis progression via targeting miR-31 and modulating RhoA/ROCK signal pathway." (PMID 39133718, 2024). "MFG-E8 carried by BM-MSC-EVs was able to reduce renal fibrosis in UUO-treated rats by inhibiting the RhoA/ROCK signaling pathway, and the biological effects of these EVs were abrogated by silencing MFG-E8." (PMID 37376163, 2023). "Research showed that extracellular vesicles produced by bone marrow mesenchymal stem cells attenuate renal fibrosis, in part by inhibiting the RhoA/ROCK pathway." (PMID 37179298, 2023). "Our results show that BMSC-EVs containing MFG-E8 attenuate renal fibrosis in a rat model of renal fibrosis, partly through RhoA/ROCK pathway inhibition." (PMID 32586368, 2020). "Targeting RhoA neddylation could represent a transformative therapeutic approach to managing renal fibrosis." (PMID 39900822, 2025). "For instance, a previous study has illuminated that BMSC-EVs containing MFG-E8 could repress renal fibrosis through RhoA/ROCK signaling pathway inhibition in a rat model." (PMID 35672285, 2022). "Interestingly, in renal fibrosis, RhoA/ROCK1 aggravates renal fibrosis by activating the NOX4/ROS signalling pathway." (PMID 32496208, 2020). "We hypothesized that BMSC-EVs containing milk fat globule–epidermal growth factor–factor 8 (MFG-E8) could attenuate renal fibrosis by inhibiting the RhoA/ROCK pathway." (PMID 32586368, 2020). "Additionally, berberine synergistically reduces renal fibrosis by suppressing the Notch/Snail pathway (downregulating Jagged1, Notch1, and Snail1) and the RhoA/ROCK pathway (reducing FN accumulation), as well as blocking the SphK1- S1P signaling cascade (decreasing S1P2 receptor expression)." (PMID 40567371, 2025). "Kaempferol showed the potential to improve histological changes and renal fibrosis while reducing the expression levels of TGF-β1, CTGF, fibronectin, collagen IV, IL-1β, RhoA, ROCK2, and P-MYPT1 in DKD renal tissue." (PMID 36466094, 2022). "Second, while our study showed that BMSC-EVs reduce renal fibrosis in part by inhibiting RhoA/ROCK, further research is needed to determine how BMSC-EVs exert antioxidant and antiapoptotic activities in the context of renal fibrosis." (PMID 32586368, 2020). "Activation of the RhoA/ROCK signalling pathway can upregulate NOX4/ROS expression, promote renal muscle fibroblast differentiation, and aggravate renal fibrosis." (PMID 32496208, 2020). "In this study, we found that BMSC-EVs can reduce renal fibrosis by producing MFG-E8, which inhibits the RhoA/ROCK pathway." (PMID 32586368, 2020). "The role of the TGF-β1 signaling cascade was confirmed in the progression of nephrolithiasis by the TGF-β1-dependent RhoA/ubiquitin-proteasome pathway and other renal diseases, such as (UUO)-induced renal fibrosis." (PMID 26193266, 2015). "Previous studies have shown that NF-κB signaling is mediated by RhoA/ROCK signaling and that TGR5 activation can inhibit RhoA/ROCK/NF-κB signaling in mouse mesangial cells and reduce the expression of FN and TGF-β1, thus alleviating renal fibrosis in DKD mice." (PMID 39371929, 2024). "The core genes SRC, IGF1, RHOA, ESR1, EGFR and CDC42 may play a key role in the inhibition of the development and progression of renal fibrosis by diosgenin." (PMID 37179298, 2023).
renal fibrosis (continued). "Thus, we postulated that BMSC-EVs attenuate renal fibrosis by delivering MFG-E8, which then regulates the RhoA/ROCK signaling pathway." (PMID 32586368, 2020). "In the study of renal disease, it was found that RhoA/ROCK1 is the upstream signal molecule of NOX4/ROS, and the activation of the RhoA/ROCK1 signal pathway can upregulate the expression of NOX4/ROS, promote the differentiation of renal myofibroblasts, and aggravate renal fibrosis." (PMID 34135982, 2021).
Alzheimer disease (18 papers, 2011 to 2025). A progressive, neurodegenerative disease characterized by loss of function and death of nerve cells in several areas of the brain leading to loss of cognitive function such as memory and language. "RhoA signaling is important in neurodegenerative diseases, such as Parkinson’s disease, Alzheimer’s disease, and Huntington’s disease, which are characterized by increased RhoA and ROCK expression, and by their inhibition, these diseases can rescue lesions." (PMID 40594855, 2025). "Previous studies have highlighted RhoA’s diverse roles in microglia, including its regulation of glutamate release in Alzheimer’s disease, where RhoA deletion exacerbates disease progression, and ATP release, which is promoted by increased RhoA activity." (PMID 40846818, 2025). "RhoA activation is a hallmark of CNS disorders, spinal cord injury (SCI), and neurodegenerative diseases like Parkinson’s disease, Huntington’s disease, Alzheimer’s disease, and amyotrophic lateral sclerosis with neuro-apoptotic and neuroinflammatory roles." (PMID 38928492, 2024). "Using previously published data, we show that genes in the RhoA/ROCK signaling cascade are highly upregulated in the neurodegenerative microglia (MGnD) from APP/PS-1 transgenic Alzheimer’s disease (AD) mice." (PMID 37408199, 2023). "For example, in Alzheimer’s disease (AD) brain, the overall RhoA levels are found to be reduced, while remaining RhoA co-localized with hyperphosphorylated tau in neurofibrillary tangles." (PMID 34054432, 2021). "Indeed, emerging evidence points toward a role of aberrant RhoA signaling in neurodegenerative diseases such as Parkinson’s disease, Alzheimer’s disease, Huntington’s disease, and amyotrophic lateral sclerosis." (PMID 35563826, 2022). "Thus, TRPV1-dependent hampering of AMPAR endocytosis might be a putative mechanism for TRPV1 positive modulation of RhoA, thus contributing to the development of Alzheimer’s disease." (PMID 33240883, 2020). "In any event, a greater understanding of RhoA signaling in the nervous system is merited, given the role of RhoA in intellectual disabilities, autism spectrum disorder, Alzheimer’s disease, Parkinson’s disease, and Timothy Syndrome, all of which exhibit altered dendritic arbors." (PMID 31461398, 2019). "In the case of Alzheimer's Disease (AD), the use of ROCK inhibitors to modulate RhoA was shown to impact on disease phenotype." (PMID 32788615, 2020). "Our findings indicate that potentiating the activity of NGF at the level of RhoA inactivation and PTP1B activation may represent a new means to combat the noxious effects of Aβ in Alzheimer's disease." (PMID 21294893, 2011). "RhoA/ROCK signaling in microglia is increasingly seen as a major contributor to the progression of neurodegenerative disorders, with RIs reducing microglial activation in animal models of amyotrophic lateral sclerosis (ALS), Parkinson’s disease (PD), and Alzheimer’s disease (AD)." (PMID 37408199, 2023).
myocardial infarction (18 papers, 2008 to 2024). Gross necrosis of the myocardium, as a result of interruption of the blood supply to the area, as in coronary thrombosis. "Nicorandil polarized macrophages into M2 phenotype by inhibiting RhoA/RhoA‐kinase pathway, which leads to attenuated myofibroblast‐induced cardiac fibrosis after myocardial infarction." (PMID 29119680, 2018). "The reducing rate of TFR in myocardial infarction area, RhoA activity, and ROCK1, ROCK2, and p-MLC protein expressions in UTR knockdown rats decreased markedly compared with that in WT rats." (PMID 29541143, 2018). "In support of our findings, another research group has recently reported that in myocardial infarction, cardiac RhoA signaling plays a role in mitochondrial quality control by regulating the function and expression of Parkin and PINK1, a protein kinase that phosphorylates and activates Parkin." (PMID 36758801, 2023). "They showed that in the heritable hyperlipidemic rabbits, which are prone to the myocardial infarction, the level of unmodified RhoA and Rac1 and the levels of a membrane-bound (geranylgeranylated) RhoA and Rac1 increased with age (assessed between 3 and 7 months)." (PMID 33379334, 2020). "In this study, we detected the effect of Rb1 on rat myocardial blood flow, myocardial infarct size, cardiac function, velocity of venule red blood cell, myocardial structure and apoptosis, energy metabolism and change in RhoA signaling pathway during cardiac I/R injury." (PMID 28327605, 2017). "Prior studies have shown that ferulic acid attenuates the migratory and proliferative capacity of cardiac fibroblasts and reduces myocardial fibrosis after myocardial infarction by inhibiting the pRB-E2F1/CCNE2 and RhoA/ROCK2 pathways." (PMID 38254195, 2024). "Finally, to elucidate the mechanism of phenomenon we observed, we found that MFA attenuated HCF differentiation after myocardial infarction by suppressing the migration and proliferation in HCFs, which was by suppressing the pRB-E2F1/CCNE2 and the RhoA/ROCK2 pathway." (PMID 34483923, 2021).
Obesity (18 papers, 2013 to 2024). Accumulation of substantial excess body fat. "Here, we propose for the first time that RhoA pathway blockage occurs to ensure a protection against obesity-induced cardiovascular risk in females." (PMID 37342890, 2023). "Further work on determining the nature of the PDZ-RhoGEF H1467R SNP variant, using functional reconstitution of PDZ-RhoGEF KO cells and mice, as well as biochemical characterization of its activity towards RhoA will be needed to fully understand its action in obesity and T2D predisposition." (PMID 26512886, 2015). "Therefore, RhoA/Rho-kinase signaling is implicated in inflammatory changes in adipose tissue in obesity, contributing to and aggravating weight gain and insulin resistance." (PMID 24490784, 2014). "Here, we focus on the current status of RhoA/ROCK research in major metabolic organs that play vital roles in the development of obesity and insulin resistance." (PMID 35769086, 2022). "Studies using chemical inhibitors, whole-body and tissue-specific genetic manipulations in animal models have demonstrated that abnormal RhoA/ROCK signaling contributes to the pathogenesis of obesity and type 2 diabetes." (PMID 35769086, 2022). "Further, we used this model to investigate the effect of hypoxia as the early stage of obesity on RhoA/ROCK signaling pathway in adipocytes." (PMID 34728615, 2021). "Concurrently, reciprocal changes for muscle RhoA expression were seen (i.e., RhoA decreased in obesity and rescued to a normal level by exercise)." (PMID 34234788, 2021). "As shown in rodent models, selective targeting RhoA/ROCK signaling in lacteals of the small intestine is clinically of significance to a novel therapeutic approach for the treatment of obesity and metabolic dysfunction." (PMID 33521001, 2020). "In the Ossabaw swine model of obesity there was an up-regulation of 186 PVAT-derived proteins associated with increased coronary contractility and these included transforming protein RhoA and calpastatin." (PMID 29479319, 2018). "RhoA-ROCK signaling is activated in mature adipocytes via mechanical stretch generated by obesity-related adipocyte hypertrophy." (PMID 26512886, 2015). "The mechanisms of how obesity leads to RhoA expression is currently under investigation; however, our previous work points to a potentially important role of isoprenoid signaling in airway regulation." (PMID 23840226, 2013). "The mechanistic source of increased RhoA expression in airway tissues of obese mice needs to be determined, as does the specific impact of this pathway on the airway pathophysiology of obesity." (PMID 23840226, 2013). "The aim of this study therefore, was to investigate the effect of obesity on the expression of various components of the RhoA/ROCK pathway in human myometrium at term pregnancy." (PMID 23948067, 2013). "Although we were not allowed to get enough tissues to isolate hADSC from MSL patients, our findings suggest that the RhoA/ROCK1/ERK1/2 signaling pathway is a potential therapeutic target for the development of drugs that prevent or treat MSL or obesity patients." (PMID 26148871, 2015). "RhoA expression is inherently increased in airway tissue from ob/ob mice, and obesity-entrained alterations in this pathway may make it a novel therapeutic target for treating airway disease in the obese population." (PMID 23840226, 2013). "Thus, inhibition of RhoA/ROCK2 in adipose tissue may provide a potential therapeutic strategy to combat obesity and insulin resistance." (PMID 35769086, 2022). "Together, all these research efforts will improve our understanding of RhoA/ROCK signaling in thermogenesis and energy expenditure with the translational goal of developing new treatment for obesity and related disease." (PMID 35769086, 2022).
Obesity (continued). "Altogether, these data demonstrate that exercise-induced amelioration of insulin sensitivity in the obesity state could be explained by exercise-mediated suppression of PTP1B and PTEN, at least in part, coupled with increased RhoA expression." (PMID 34234788, 2021). "Therefore, hypoxia and its downstream mechanical pathways, including MKL1 that is regulated via RhoA/ROCK signaling pathway, can be used as a potential target for treating the early stage of obesity." (PMID 34728615, 2021). "Also, the level of RhoA protein in skeletal muscle, an upstream mediator of ROCK2, was reduced by obesity." (PMID 34234788, 2021). "Hypertrophy in response to obesity-induced metabolic and haemodynamic demands.Enhanced function via increased sodium and water reabsorption through SGLT1 and SGLT2, with pathophysiological mechanisms including lipid accumulation, activation of RAS and RhoA and aberrant hypoxic responses." (PMID 39050867, 2024). "Moreover, RhoA/ROCK-mediated actomyosin contractility promotes nuclear translocation of the transcriptional co-activators YAP/TAZ which suppress expression of pro-apoptotic factor Bim and protect against white adipocyte cell death during obesity." (PMID 35769086, 2022). "Considering recent advances in understanding RhoA/ROCK signaling in regulating metabolic functions, promoting brown adipogenesis and browning process of WAT by ROCK inhibition, particularly ROCK2 inhibition, have emerged as promising strategies to treat obesity and its related metabolic disorders." (PMID 35769086, 2022). "Moreover, mice lacking RhoA in hypothalamic tyrosine hydroxylase neurons showed increased sensitivity to ghrelin and decreased sensitivity to leptin, resulting in increased food intake and development of obesity." (PMID 35769086, 2022).
Cognitive impairment (17 papers, 2014 to 2025). Abnormal cognition is characterized by deficits in thinking, reasoning, or remembering. "In this study, we showed that TBI causes motor and cognitive impairments in mice that are alleviated by genetically or pharmacologically blocking RhoA-ROCK signaling." (PMID 28878396, 2017). "PirB knockdown alleviated synaptic deficits and cognitive impairment after CSR by inhibiting the RhoA/ROCK2/LIMK1/cofilin signalling pathway." (PMID 36417104, 2023). "RhoA has been reported to modulate synaptic plasticity and inhibition of the RhoA pathway reduces cognitive impairment and deficits in synapses and dendritic spines." (PMID 36268187, 2022). "The cognitive deficits reported for Ophn1−/y mice have been proposed to result from over-activation of the RhoA signalling pathways." (PMID 24800744, 2014). "Furthermore, recent findings have revealed that the m6A modification of RHOA can be inherited by offspring, contributing to hippocampal neuron aging and cognitive impairments induced by environmental factors such as cadmium exposure and a high-fat diet." (PMID 39859306, 2025). "Furthermore, 50-54% of rats in the tMCAO90min group developed significant cognitive impairment on day 28, and thalamic NgR1, RhoA, and ROCK expression were greater in tMCAO90min rats than in sham rats." (PMID 34630954, 2021). "Moreover, we identified that fasudil could mimic the beneficial effect of PirB knockdown and ameliorate synaptic deficits and cognitive impairment, which further demonstrated that the RhoA/ROCK2/LIMK1/cofilin signalling pathway is downstream of PirB in CSR." (PMID 36417104, 2023). "Nevertheless, the correlations between the RhoA/ROCK1 and EGFR/PI3K/Akt signaling pathways and the key factors involved in the occurrence of surgery-induced cognitive impairment need further experimental verification." (PMID 39781463, 2025). "Additionally, intervention in the RhoA/ROCK2 signaling pathway via pharmacological approaches and genetic modification attenuates the phosphorylation of radixin, thereby mitigating cognitive impairments induced by sevoflurane." (PMID 38825816, 2024). "In this study, we demonstrated that RES could significantly prevent SEV-induced brain injury by reducing neuronal apoptosis and cognitive impairment, which was at least partly mediated by the SIRT1/RhoA signaling pathway in adult rats." (PMID 34247566, 2022). "Increased NgR1/RhoA/ROCK expression and insufficient increase in expression of their antagonist LOTUS could be involved in poststroke cognitive impairment." (PMID 34630954, 2021). "Moreover, downregulation of Nogo-A led to alleviation of the cognitive impairment and microvascular dysfunction as well as the inhibition of the expression of S1PR2 and the RhoA/ROCK signaling pathway." (PMID 34830564, 2021). "Therefore, an approach that inhibits AGEs-RAGE induced activation of RhoA/ROCK/moesin signaling pathway is expected to attenuate the cerebral microangiopathy and thus prevent the cognition impairment in T2DM." (PMID 29867568, 2018). "Finally, we investigated whether RhoA/ROCK2 pathway inhibition using fasudil, a widely used ROCK2 inhibitor, has therapeutic effects on cognitive impairment and synaptic deficits following CSR." (PMID 36417104, 2023). "Altogether, these data reveal that CSR-mediated activation of the RhoA/ROCK2/LIMK1/cofilin signalling cascade via the PirB receptor may result in abnormal actin dynamics and actin rearrangement, ultimately leading to synaptic deficits and cognitive impairment." (PMID 36417104, 2023). "Therefore, the purpose of this study was to investigate the role of SIRT1/RhoA signaling in the neurotoxicity induced by long-term SEV exposure and the effect and mechanism of RES administered in advance and postoperatively on cognitive impairment in adult rats." (PMID 34247566, 2022).
Cognitive impairment (continued). "Moreover, we found that fasudil, a widely used ROCK2 inhibitor, could mimic the beneficial effect of PirB knockdown and ameliorate synaptic deficits and cognitive impairment, further demonstrating that PirB induced cognitive dysfunction after CSR via the RhoA/ROCK2/LIMK1/cofilin signalling pathway." (PMID 36417104, 2023).